CFAP210 (cilia and flagella associated protein 210)
Description:
Microtubule inner protein (MIP) part of the dynein-decorated doublet microtubules (DMTs) in cilia axoneme, which is required for motile cilia beating.
Synonyms: C2orf77; CCDC173; LOC129881
Tractability: Small molecule: a structure with a bound ligand is known.
Gene: Protein-coding gene on chromosome 2 (169,645,425 to 169,694,405, reverse strand). Ensembl gene ENSG00000154479.
Subcellular location: Cytoplasm, cytoskeleton, cilium axoneme; Cytoplasm, cytoskeleton, flagellum axoneme
Gene Ontology:
Biological process: flagellated sperm motility
Cellular component: axonemal microtubule; axoneme; axonemal B tubule inner sheath; sperm flagellum; polymeric cytoskeletal fiber
Genetic constraint (gnomAD): Loss-of-function variants: 70 observed, 63.54 expected, observed/expected ratio (o/e) 1.1, 90% interval 0.91 to 1.34. The upper end of that interval is the gene's LOEUF score, 1.34, which puts it in group 5 of 6, group 1 being the genes least tolerant of losing a copy. Missense variants: 606 observed, 630.8 expected, observed/expected ratio (o/e) 0.96, 90% interval 0.9 to 1.03. Synonymous variants: 197 observed, 194.35 expected, observed/expected ratio (o/e) 1.01, 90% interval 0.9 to 1.14.
Homologues: Orthologues: chimpanzee CFAP210 (99% identical), macaque CFAP210 (97% identical), dog CFAP210 (85% identical), pig CFAP210 (85% identical), rabbit CFAP210 (84% identical), guinea pig CFAP210 (80% identical), rat Cfap210 (75% identical), mouse Cfap210 (74% identical).